LEP (leptin)
Diseases named in the same sentence as LEP in open-access papers (continued):
Sharing a sentence is not in itself a finding about the gene and the disease.
delirium (4 papers, 2019 to 2025). A disorder characterized by confusion; inattentiveness; disorientation; illusions; hallucinations; agitation; and in some instances autonomic nervous system overactivity. "Other hormones, such as estradiol or leptin, may have a role in delirium pathophysiology, but additional research is needed to confirm this hypothesis." (PMID 37251808, 2023). "Cortisol and leptin were the two reported hormones with a possible link to postoperative delirium." (PMID 31263968, 2019). "Leptin levels were significantly lower in patients with delirium compared to those without." (PMID 31263968, 2019).
diabetic neuropathy (4 papers, 2013 to 2018). A chronic, pathological complication associated with diabetes mellitus, where nerve damages are incurred due to diabetic microvascular injury involving small blood vessels that supply these nerves, resulting in peripheral and/or autonomic nerve dysfunction. "In patients with diabetic neuropathy, leptin was significantly associated with SDNN (r = −0.323, p = 0.02) or SDANN5 (r = −0.338, p = 0.014)." (PMID 26338087, 2015). "Since determination of cornea nerve density and function are noninvasive and surrogate markers for diabetic neuropathy, the ZDSD rat with its functional leptin pathway may be a good model for preclinical testing of treatments for diabetic neuropathy." (PMID 25371906, 2014).
dilated cardiomyopathy (4 papers, 2013 to 2023). Cardiomyopathy which is characterized by dilation and contractile dysfunction of the left and right ventricles. "In vitro experiments using cardiomyocytes from either patients with dilated cardiomyopathy or controls indicate that leptin acts in concert with resistin causing a TNF-α- and IL6-dependent cardiac redox stress response." (PMID 32655492, 2020).
Down syndrome (4 papers, 2012 to 2025). "A study conducted on Ts65Dn mice, a partial trisomy model of Down syndrome, observed elevation of leptin, galectin-3, and heat shock protein A 72 (HSPA 72), which are linked with autoimmunity." (PMID 40356974, 2025). "Increased levels of leptin have been observed in children and youth with Down syndrome, potentially influencing leptin resistance and an ability to suppress appetite and regulate body weight." (PMID 37497298, 2023). "Moreover, increased leptin, glucose, and thyroid hormone imbalance have been reported in Egyptian children with Down syndrome." (PMID 40356974, 2025).
female infertility (4 papers, 2022 to 2024). Diminished or absent ability of a female to achieve conception. "Furthermore, even if implantation failure is a complex and multifactorial event, the down-secretion of leptin by the endometrium could be a biochemical cause behind female infertility, suggesting that restoration of leptin levels may be a new approach for the treatment of IF in women." (PMID 38999965, 2024). "The effect of irisin and leptin on modulation of 84 genes involved in female infertility was evaluated by using qRT-PCR array." (PMID 35028351, 2022).
focal glomerulosclerosis (4 papers, 2012 to 2024). "Previous research showed that infusion of leptin into healthy rats for 3 weeks, caused proteinuria due to the development of focal glomerulosclerosis." (PMID 38627329, 2024). "It was recently shown that, in rats, infusion of recombinant leptin caused the development of focal glomerulosclerosis." (PMID 22666590, 2012). "Moreover, infusion of recombinant leptin in rats triggered the development of focal glomerulosclerosis." (PMID 35619087, 2022). "The underlying mechanisms may include renin-angiotensin-aldosterone system activation, leptin, adiponectin, fetuin-A, and adipose tissue inflammation, as factors that contribute to glomerulonephritis, focal and segmental glomerulosclerosis, and IgA nephropathy." (PMID 26651346, 2015).
folate deficiency (4 papers, 2019 to 2023). A nutritional condition produced by a deficiency of FOLIC ACID in the diet. "Our previous study on folate deficiency increased leptin production of adipocytes implying that there are interactions among folate status, leptin, and immunoregulation." (PMID 37630806, 2023). "We have previously shown that both HFF diet and folate deficiency increased lipid accumulation and leptin production." (PMID 37630806, 2023). "In the current study, we also confirmed that both HFF diet and folate deficiency significantly increased renal leptin levels in mice." (PMID 37630806, 2023). "Our data demonstrated that folate deficiency increased fat mass, adipocyte size, higher serum leptin level, and hepatic triglyceride (TG) accumulation." (PMID 35548560, 2022). "Our results suggested that folate deficiency increased lipid accumulation and leptin production of adipocytes, and thus, inadequate folate status might be one of the risk factors for adiposity." (PMID 35548560, 2022). "The results showed that folate deficiency together with a high-fat diet (HFS-f0, HF-f0, HFF-f0) had higher WAT mass, adipocyte size, serum leptin level, and hepatic TG compared to those of the folate-sufficient groups (HFS-f1, HF-f1, and HFF-f1)." (PMID 35548560, 2022). "Specifically, folate deficiency led to decreased NPY expression and to overexpression of AgRP mRNA, along with reduced expression of the leptin and insulin receptors, whereas ghrelin overexpression was associated with reduced expression of these receptors." (PMID 31615150, 2019). "The positive correlation between leptin and phosphorylated STAT3 ratio, as well as TGF-β1 and phosphorylated Smad2/3 ratio in renal tissues, revealed the mechanisms of effects of the HFF diet and folate deficiency." (PMID 37630806, 2023).
gastrointestinal infection (4 papers, 2013 to 2025). "In the same cohort, approximately 40% of children with leptin or leptin receptor deficiency developed gastrointestinal infections with severe diarrhea requiring hospitalization and 38–55% had recurrent respiratory infections including pneumonia." (PMID 40944251, 2025). "However, leptin is secreted by colonic epithelial cells during acute inflammation, and both micro- and macro-parasitic intestinal infections can disrupt its production,71, –73 so a causative relationship is also plausible." (PMID 36096405, 2022). "Furthermore, we demonstrate for the first time an immunoendocrine feedback loop, in which CD4+ T-cell driven weight loss via CCK reduces leptin levels which impinge on CD4+ T-cell driven effector mechanisms for gastrointestinal infection resolution." (PMID 23349631, 2013). "We have therefore identified a novel molecular pathway and can include I-cell hyperplasia and weight loss as an adaptively driven immune response which, through alterations in leptin, is beneficial during intestinal infection." (PMID 23349631, 2013).
head and neck cancer (4 papers, 2014 to 2024). A primary or metastatic malignant neoplasm affecting the head and neck. "We delve into the potential mechanisms by which NAT facilitate cervical lymph node metastasis in head and neck cancer, particularly through the secretion of adipokines such as leptin, adiponectin, and Interleukin-6." (PMID 38800384, 2024). "Cytokine level changes may be able to serve as biomarkers for treatment response and survival outcomes, and leptin levels may be a potential biomarker for cachexia development in patients with head and neck cancer." (PMID 38534979, 2024).
HELLP syndrome (4 papers, 2010 to 2023). A life-threatening condition that can potentially complicate pregnancy. "There is a lack of information on the role of LEPR and its polymorphisms on the leptin levels in PE and HELLP syndrome." (PMID 20149225, 2010). "There are several studies showing higher expression of the leptin gene in microarray experiments in PE and HELLP syndrome." (PMID 20149225, 2010). "Several studies have shown overexpression of leptin in microarray experiments in pre-eclampsia (PE) and in hemolysis, elevated liver enzymes, low platelets (HELLP) syndrome." (PMID 20149225, 2010). "Adiponectin and leptin were quantitated in first-trimester blood samples (gestational week 10+3–13+6) from 126 women who later developed PE with proteinuria (98 mild PE; 21 severe PE; 7 HELLP syndrome), and 297 controls, recruited from the Copenhagen First-Trimester Screening Study." (PMID 36676079, 2023).
helminth infection (4 papers, 2018 to 2025). "Elevated levels of interleukin (IL)-10, IL-6, and leptin have been associated with helminth infection and leprosy, respectively." (PMID 41239264, 2025). "Serum levels of IL-10, IL-6, and leptin are known to be raised in leprosy patients and in helminth infection patients, respectively." (PMID 41239264, 2025). "For leprosy with helminth infection, the mean IL-10, IL-6, and leptin serum levels were 86.43 pg/ml ± 4.34 pg/ml, 447.42 pg/ml ± 122.15 pg/ml, and 19,272.85 pg/ml ± 4,065.23 pg/ml, respectively." (PMID 41239264, 2025). "In the present study, we investigated the expression of main adipokine adiponectin and leptin in response to T. spiralis infection and further elucidate the role and regulation of adiponectin in immune response to helminth infection." (PMID 37635188, 2023). "In an attempt to determine the involvement of adipokines during gastrointestinal helminth infection, we examined the expression of adiponectin and leptin in the serum and intestinal tissue of mice infected with T. spiralis at 7 and 14 days post-infection." (PMID 37635188, 2023). "Helminth infections in the intestines affect the concentration of leptin in the blood." (PMID 41239264, 2025). "In this study, the average IL-10, IL-6, and leptin serum levels in leprosy patients with helminth infections were higher than those without helminth infection." (PMID 41239264, 2025). "Meanwhile, the mean IL-10, IL-6, and leptin serum levels for leprosy without helminth infection were 72.97 pg/ml ± 14.69 pg/ml, 161.77 pg/ml ± 63.98 pg/ml, and 14,649.07 pg/ml ± 2,002.66 pg/ml, respectively." (PMID 41239264, 2025). "To determine the mechanism by which helminth infection may alter HFD-induced body weight gain, we analyzed gene expression of key regulators mediating lipid metabolism in gonadal fat, including leptin, C/EBPα, and PPARγ." (PMID 29545532, 2018). "However, the Mann-Whitney test revealed a p-value of 0.062 (p > 0.05) for serum leptin levels between leprosy patients with and without helminth infections." (PMID 41239264, 2025). "However, based on the Mann-Whitney test, the serum level of leptin between leprosy patients with and without helminth infections was p = 0.062." (PMID 41239264, 2025). "However, it remains unclear whether or not the increased ratio of adiponectin and leptin in the circulation following helminth infection may involve in the consequence of helminth infection on an improved metabolic function." (PMID 37635188, 2023).
hypersomnia (4 papers, 2021 to 2026). A sleep disorder characterized by excessive sleepiness. "Large-scale genomic studies identified shared genetic liabilities between symptoms of hyperphagia, hypersomnia and weight gain during a depressive episode and traits such as elevated CRP, leptin, and body mass index (BMI), partially explaining their phenotypic connection." (PMID 37301859, 2023).
idiopathic scoliosis (4 papers, 2009 to 2025). A scoliosis with no known cause. "Female adolescents with idiopathic scoliosis with low BMD showed reduced leptin levels compared to healthy female controls." (PMID 40076690, 2025).
insulin-resistant diabetes (4 papers, 2013 to 2024). "Leptin can partly replace the absence of adipose tissue in lipodystrophic patients, who develop insulin-resistant diabetes and elevated triglycerides." (PMID 23781317, 2013).
leishmaniasis (4 papers, 2018 to 2025). Infectious disease that is transmitted through the bite of hematophagous female phlebotomine sand flies. "Leishmaniasis is a vector-borne intracellular infectious disease caused by the protozoan Leishmania sp., For the first time, we have hypothesized the possible role of leptin in human VL." (PMID 29868503, 2018). "The synergistic effect observed when leptin is combined with glucantime offers promising therapeutic potential for leishmaniasis treatment, potentially allowing for reduced drug doses and associated toxicity while maintaining or enhancing efficacy." (PMID 40855340, 2025). "Thereafter, several studies on the relationship between leptin and disease outcome in leishmaniasis, indicated that exogenous recombinant leptin augmented the host protective immunity with the combination of miltefosine in mouse macrophages (J774.1 cell line) during in vitro L. donovani infection." (PMID 29868503, 2018).
LEPR deficiency (4 papers, 2020 to 2024). "An appreciation of the severe impact of LEP or LEPR deficiency on morbidity and early mortality, educational attainment, and the attendant stigmatization should spur efforts to deliver the available life-saving drugs to these children as a matter of urgency." (PMID 37659411, 2023). "The treatments include hormone replacement therapy with recombinant leptin for subjects with LEP deficiency, the MC4R agonist setmelanotide for LEPR deficiency, and glucagon-like peptide-1 receptor agonists for subjects with MC4R deficiency." (PMID 37659411, 2023).
lupus nephritis (4 papers, 2017 to 2025). Glomerulonephritis in the context of systemic lupus erythematosus. "The aim of this study was to evaluate the relationship between serum leptin and adiponectin levels with severity of proteinuria secondary to lupus nephritis (LN)." (PMID 28898254, 2017). "Because it inhibits the proliferation of Treg cells, leptin, a pro-inflammatory adipocytokine, is unusually increased in SLE patients and speeds up the course of lupus nephritis." (PMID 41476956, 2025).
metabolism (4 papers, 2018 to 2021). "This increase in TG concentration in serum also induced secretion of cytokines, that is, leptin and IL-6, which are known to have an association with impaired glucose metabolism and insulin sensitivity." (PMID 30319558, 2018).
metastatic cancer (4 papers, 2016 to 2024). A carcinoma which has spread from the original site of growth to another anatomic site. "This leptin-dependent phenotype associated to the activation of FAK and Src is consistent with the aggressive phenotype of the tumorigenic and metastatic cancer cells." (PMID 31671408, 2019). "In this review, we examined the impact of adipocytes on cancer by describing the adipocyte-secreted factors that are involved in controlling metastatic cancer, focusing on adipokines, such as adiponectin, leptin, visfatin, chemerin, resistin, apelin, and omentin." (PMID 38238841, 2024). "Acquired resistance to leptin and/or insulin is likely to interfere with this signaling and increase the risk of metastatic cancer; the lack of reaction of DLD-1 cells to leptin in our study illustrates such dysfunction on the cellular level." (PMID 27842582, 2016).
Monogenic obesity (4 papers, 2023 to 2025). "Monogenic obesity usually presents in early childhood and is due to a single gene disease-causing variant(s), mainly genes implicated in the leptin–melanocortin pathway, leading to defects in the regulation of hunger and satiety in the hypothalamus." (PMID 37329217, 2023).
obesity-hypoventilation syndrome (4 papers, 2018 to 2025). Hypoventilation syndrome in very obese persons with excessive adipose tissue around the abdomen and diaphragm is characterized by diminished to absent ventilatory chemoresponsiveness; chronic hypoxia; hypercapnia; polycythemia; and long periods of sleep during day and night (hypersomnolence). "Accordingly, this relative leptin-deficient or -resistant state is thought to contribute to the genesis of obesity hypoventilation syndrome, whereby ineffective leptin axis functioning within the CNS is thought to provoke hypoventilation." (PMID 38542217, 2024). "Research indicates that serum leptin levels are strongly correlated with both body fat and lung function, and that elevated leptin levels contribute to obesity hypoventilation syndrome (OHS)." (PMID 40809439, 2025).
Osteopenia (4 papers, 2014 to 2021). Osteopenia is a term to define bone density that is not normal but also not as low as osteoporosis. "Leptin signaling is required for normal skeletal maturation; leptin deficiency in growing mice results in reduced longitudinal bone growth, osteopenia, and osteopetrosis." (PMID 34202651, 2021). "Contrary to expectation, leptin deficiency did not alter the magnitude of HU-induced osteopenia in the mouse femur." (PMID 31249331, 2019). "In summary, leptin deficiency did not attenuate HU-induced osteopenia in male mice, suggesting that leptin is not required for bone loss induced by unweighting." (PMID 31249331, 2019). "In Burwell’s hypothesis, altered leptin sensitivity resulting in increased sympathetic nervous system (SNS) activity may contribute to osteopenia, skeletal overgrowth, and spinal skeletal length asymmetries." (PMID 27447624, 2016). "The implication of these findings, whether there was increased response of trabecular bone to changes in the biochemical milieu in AIS and/or whether altered leptin bioavailability plays a role in the etiopathogenesis of AIS and its accompanying osteopenia warrant further studies." (PMID 24516571, 2014).
osteopetrosis (4 papers, 2016 to 2025). Osteopetrosis, also known as marble bone disease, is a descriptive term that refers to a group of rare, heritable disorders of the skeleton characterized by increased bone density on radiographs. "Leptin-deficient (ob/ob) and leptin receptor (Lepr)-deficient db/db mice develop a mild form of osteoclast-rich osteopetrosis, most evident in long bone epiphyses, implying leptin is important for normal replacement of cartilage during skeletal maturation." (PMID 40507931, 2025). "Leptin signaling deficiency results in a mild form of osteoclast-rich osteopetrosis that persists long after normal skeletal maturation." (PMID 40507931, 2025). "Reduced epiphyseal growth in long bones of leptin signaling-deficient mice is associated with severe abnormalities in growth plate architecture and mild osteopetrosis." (PMID 40507931, 2025). "A genetic-based deficiency in leptin synthesis in mice also results in pathological alterations in growth plate architecture, a mild form of osteoclast-rich osteopetrosis, and bone compartment-specific abnormalities in cancellous bone microarchitecture, all correctable by leptin replacement." (PMID 40507931, 2025).
osteosarcoma (4 papers, 2019 to 2025). A usually aggressive malignant bone-forming mesenchymal neoplasm, predominantly affecting adolescents and young adults. "In a previous study we showed that high leptin levels and abundant numbers of MSCs characterize the osteosarcoma-associated microenvironment." (PMID 32289750, 2020). "Recent evidence has shown that leptin induces autophagy in breast, colorectal, and osteosarcoma cell lines, suggesting that autophagy has an important role in the pro-tumorigenic effects induced by leptin." (PMID 33763424, 2021). "Although MSCs abound in the osteosarcoma (OS) microenvironment, and leptin exhibits pro-tumorigenic properties, leptin’s influence on OS progression and chemoresistant signaling in MSCs remains unclear." (PMID 32289750, 2020). "In a previous study using similar EI-CM samples, multi cytokine assay has identified interleukin 6 (IL-6) and leptin as molecular candidates to induce increase of osteosarcoma cell proliferation; however neither IL-6 nor leptin have been able to mimic the pro-proliferative effects of EI-CM." (PMID 31717935, 2019). "Hence, the treatment of MSCs, a component of the osteosarcoma microenvironment, with leptin, a regulator of osteoblastogenesis characteristic of metastasis in bone cancer, stimulated autophagy and activated TGF-β signaling that corresponded to cisplatin resistance in osteosarcoma cells." (PMID 40486962, 2025).